RIPK4 (receptor interacting serine/threonine kinase 4)
Description:
Serine/threonine protein kinase (By similarity). Required for embryonic skin development and correct skin homeostasis in adults, via phosphorylation of PKP1 and subsequent promotion of keratinocyte differentiation and cell adhesion (By similarity). It is a direct transcriptional target of TP63. Plays a role in NF-kappa-B activation.
Synonyms: ANKRD3; DIK; ANKK2; RIP4; PKK; CHANDS; NKRD3; PPS2
Tractability: Small molecule: a high-quality ligand is known; it belongs to a druggable protein family. Antibody: its Gene Ontology location is reachable by antibodies, with high confidence; UniProt places it where antibodies can reach, with medium confidence. PROTAC: UniProt records ubiquitination sites on it; ubiquitination databases record sites on it; a small molecule that binds it is known.
Target class: TKL protein kinase group; Enzyme; Kinase; TKL protein kinase RIPK family; Protein Kinase
Gene: Protein-coding gene on chromosome 21 (41,739,369 to 41,767,089, reverse strand). Ensembl gene ENSG00000183421.
Subcellular location: Cytoplasm; Membrane
Subcellular location (Human Protein Atlas): Cytosol; Vesicles; Plasma membrane
Gene Ontology:
Molecular function: protein binding; protein serine kinase activity; ATP binding; protein kinase activity; protein serine/threonine kinase activity
Biological process: intracellular signal transduction; morphogenesis of an epithelium; skin development
Cellular component: cytoplasm; membrane
Genetic constraint (gnomAD): Loss-of-function variants: 17 observed, 44.2 expected, observed/expected ratio (o/e) 0.38, 90% interval 0.26 to 0.58. The upper end of that interval is the gene's LOEUF score, 0.58, which puts it in group 2 of 6, group 1 being the genes least tolerant of losing a copy. Missense variants: 897 observed, 1,106.4 expected, observed/expected ratio (o/e) 0.81, 90% interval 0.77 to 0.86. Synonymous variants: 498 observed, 497.28 expected, observed/expected ratio (o/e) 1, 90% interval 0.93 to 1.08.
Homologues: Orthologues: chimpanzee RIPK4 (99% identical), macaque RIPK4 (98% identical), mouse Ripk4 (91% identical), rat Ripk4 (91% identical), dog RIPK4 (90% identical), pig RIPK4 (89% identical), guinea pig RIPK4 (89% identical), zebrafish ripk4 (60% identical), tropical clawed frog ripk4 (59% identical). Paralogues in human: ANKK1 (36% identical).
Diseases named in the same sentence as RIPK4 in open-access papers:
RIPK4 is named in the same sentence as 68 diseases in open-access papers, as found by Europe PMC text mining. Sharing a sentence is not in itself a finding about the gene and the disease. The quoted sentences say what the papers report.
ovarian carcinoma (12 papers, 2015 to 2024). A malignant neoplasm originating from the surface ovarian epithelium. "RIPK4 can function as a potential independent risk factor for overall survival and biomarker in evaluating the prognosis of ovarian cancer." (PMID 34124253, 2021). "In ovarian cancer, elevated RIPK4 expression has been correlated with more adverse progression, and its inhibition decreased metastasis in in vitro experiments." (PMID 38139812, 2023). "RIPK4 expression is up-regulated and relates with a poor prognosis in ovarian cancer, cervical SCC, pancreatic cancer, bladder cancer and osteosarcoma." (PMID 35186499, 2022). "By contrast, RIPK4 overexpression predicts poor prognosis in patients with ovarian cancer, cervical SCC, pancreatic cancer, bladder cancer, and osteosarcoma." (PMID 35186499, 2022). "RIPK4 is also identified as a target gene of miR-330-3p, which can suppress the proliferation, migration and invasion of ovarian cancer cells." (PMID 35186499, 2022). "More data from multiple cohorts and more evidence from laboratory are needed to verify the prognostic role of RIPK4 in ovarian cancer and the regulatory pathway which RIPK4 is involved in." (PMID 34124253, 2021). "The present study demonstrated the adverse impacts of RIPK4 overexpression on the prognosis of human ovarian cancer and the pivotal role of RIPK4 in promoting tumor metastasis." (PMID 34124253, 2021). "This study was conducted to evaluate the prognostic value of receptor-interacting protein kinase 4 (RIPK4) in ovarian cancer (OC) and its role in tumorigenesis." (PMID 34124253, 2021). "More and more evidences have shown that RIPK4 is up-regulated in tumor tissues and promotes the occurrence and progression of cervical cancer and ovarian cancer." (PMID 30918839, 2019). "RIPK4 overexpression contributes to the progression of ovarian cancer in a xenograft tumor model." (PMID 35186499, 2022). "RIPK4 has been implicated in multiple cancer types, but its role in ovarian cancer (OC) has not been clearly elucidated." (PMID 33855091, 2021). "RIPK4 can regulate the Wnt signaling pathway thereby having an effect on ovarian carcinoma." (PMID 34124253, 2021). "However, further investigations are needed to elucidate the specific molecular mechanisms of RIPK4 in ovarian cancer." (PMID 34124253, 2021). "RIPK4 knockdown in A2780 and COV434 ovarian cancer cells could inhibit β-catenin accumulation and RIPK4 overexpression could promote ovarian cancer in a xenograft tumor model." (PMID 32923402, 2020). "Moreover, RIPK4 was significantly upregulated in several types of cancer, including ovary, colorectal and skin tumors, and elevated RIPK4 expression promoted ovarian cancer in a xenograft tumor model." (PMID 26148476, 2015). "Given that RIPK4 has been shown to play a role in the activation of the NF-κB pathway, and its expression negatively correlates with the predicted presence of T cells in human ovarian cancer, we reasoned that RIPK4 may be modulating the tumor microenvironment." (PMID 38744952, 2024). "Based on these, we try to explore whether RIPK4 was a target gene of miR-330-3p in ovarian cancer." (PMID 33487072, 2021). "Excluding the genes that have been reported and studied, we found RIPK4 that is not fully investigated in ovarian carcinoma according to the existing researches." (PMID 34124253, 2021).
cervical cancer (11 papers, 2015 to 2022). A primary or metastatic malignant neoplasm involving the cervix. "The molecular mechanism underlying RIPK4-induced proliferation and metastasis in cervical cancer cell lines warrants further study." (PMID 26148476, 2015). "Receptor interacting protein serine/threonine kinase 4 (RIPK4) is one of the receptor-interacting proteins (RIPs) that is abnormally expressed in several cancers, including bladder and cervical cancers." (PMID 36358656, 2022). "A recent study revealed that RIPK4 can influence the biological properties of malignancies, such as pancreatic, bladder, and cervical cancers." (PMID 35907206, 2022). "RIPK4 promoted invasion and metastasis of cervical cancer cells by inhibiting expression of 'vimentin, MMP2 and fibronectin which were pivotal molecules of epithelial-mesenchymal transition process." (PMID 33487072, 2021). "For instance, similar results for the expression and prognostic value of RIPK4 were reported in pancreatic cancer, cervical cancer, and colorectal cancers." (PMID 33855091, 2021). "Susan and colleagues demonstrated that RIPK4 contributed to lymph node metastasis and predicted favorable prognosis in cervical cancer." (PMID 33487072, 2021). "To further investigate the functional role of RIPK4 in cervical cancer cells, we silenced its expression using two specific small interference RNAs (siRNAs) in SiHa and Caski cells." (PMID 26148476, 2015). "We also demonstrated that depletion of RIPK4 in cervical cancer cell lines using siRNA inhibited cell proliferation, migration and invasion capacity in vitro." (PMID 26148476, 2015). "Collectively, these data suggested that RIPK4 played an important role in the growth of cervical cancer cells." (PMID 26148476, 2015). "It was reported that up-regulation of RIPK4 might help the development of certain tumors, such as skin, ovarian, cervical squamous cell carcinoma, and cervical cancer." (PMID 33119597, 2020). "Furthermore, the oncogenic function and molecular mechanism of RIPK4 were verified in cervical cancer cell lines." (PMID 26148476, 2015). "Our results suggested that RIPK4 was a novel oncogene in CSCC that could be used as an additional diagnostic and prognostic marker and potential therapeutic target for cervical cancer patients." (PMID 26148476, 2015). "Ablation of RIPK4 significantly inhibited cell proliferation of cervical cancer cells in vitro." (PMID 26148476, 2015). "Besides, high-level expression of RIPK4 promoted lymph node metastasis in cervical cancer." (PMID 33487072, 2021). "Knockdown of RIPK4 reduced cell migration and invasion via inhibition of Vimentin, MMP2 and Fibronectin expression in cervical cancer cells." (PMID 26148476, 2015). "Further studies revealed that suppression of RIPK4 expression significantly inhibited Vimentin, MMP2 and Fibronectin expression in two cervical cancer cell lines." (PMID 26148476, 2015). "To further explore the underlying mechanism of RIPK4 in promoting the migration and invasion of cervical cancer cells, we measured Vimentin, MMP2 and Fibronectin mRNA expression in RIPK4-siRNA-transfected cells and control cells." (PMID 26148476, 2015). "RIPK4 can combine with EZH2, which is a polycomb group of genes that regulates epidermal–mesenchymal transformation and angiogenesis via suppressing tumor suppressor genes, to enhance lymph node metastasis in cervical cancer." (PMID 34124253, 2021). "However, the expression and clinical significance of RIPK4 have not yet been elucidated in cervical cancer." (PMID 26148476, 2015).
pancreatic cancer (11 papers, 2019 to 2025). "RIPK4 activates the RAS/RAF/MEK/ERK pathway in pancreatic cancer by promoting the degradation of phosphatidylethanolamine binding protein 1 (PEBP1)." (PMID 36765875, 2023). "In pancreatic cancer, RIPK4 can promote cell migration and invasion via the phosphatidylethanolamine binding protein 1 (PEBP1) degradation-induce activation of the RAF1/MEK/ERK signaling pathway." (PMID 35186499, 2022). "In contrast, RIPK4 facilitated pancreatic cancer cell migration and invasion via the phosphatidylethanolamine binding protein 1 (PEBP1) degradation-induced activation of the RAF1/MEK/ERK pathway." (PMID 35186499, 2022). "Previous studies have revealed that RIPK4 is overexpressed and promotes malignant progression in bladder urothelial, nasopharyngeal, cervical, colorectal, and pancreatic cancers." (PMID 33855091, 2021). "Compared to normal pancreatic tissues, RIPK4 was upregulated in the subgroup of pancreatic cancer with a high metastatic potential." (PMID 32923402, 2020). "In addition, studies have reported that the expression of RIPK4 in cervical squamous cell carcinoma and pancreatic cancer is higher than that in normal tissues and that high expression of RIPK4 is related to a poor prognosis." (PMID 34222329, 2021). "Notably, as a downstream signaling molecule of PKCδ, RIPK4 overexpression promoted pancreatic cancer cell migration and invasion via the proteasome-mediated PEBP1 degradation-induced activation of the RAF1/MEK/ERK signaling pathway." (PMID 32923402, 2020). "Furthermore, protein kinase RIPK4 promotes the invasiveness of bladder urothelial carcinoma and pancreatic cancer through nuclear factor‐κB pathway and RAF1/MEK/ERK pathway, respectively." (PMID 31273792, 2020). "For example, among the 8 downregulated genes, RIPK4 (receptor-interacting serine/threonine kinase 4) promotes pancreatic cancer cell migration and invasion by activating RAF1/MEK/ERK signaling; presumably, RIPK4 downregulation in oocytes may also inactivate Erk signaling and impair oocyte quality." (PMID 30786262, 2019). "By contrast, increased RIPK4 expression predicts a poor prognosis in cervical SCC, pancreatic cancer, bladder cancer, and osteosarcoma." (PMID 32923402, 2020). "The phosphorylation of phosphatidylethanolamine binding protein 1 (PEBP1)—a suppressor of the BRAF/MEK/ERK pathway—via RIPK4 observed in pancreatic cancer did not occur in melanoma." (PMID 36765875, 2023).
melanoma (10 papers, 2018 to 2026). A malignant, usually aggressive tumor composed of atypical, neoplastic melanocytes. "Nonetheless, they also demonstrate that the loss of RIPK4 function activates compensatory phenotypic shifts in melanoma cells that fail to fully rescue their invasive potential." (PMID 41660747, 2026). "In this study, we examined how the downregulation and overexpression of RIPK4 affect the sensitivity of BRAF-mutated melanoma cells (A375 and WM266.4) to CisPt and DOX along with determining the underlying mechanism." (PMID 39766280, 2024). "We focused on RIPK4-dependent differentially expressed genes (DEG) associated with inflammation in WM266.4 melanoma cells which exhibit high levels of RIPK4 expression." (PMID 38656555, 2024). "For this purpose, the gene encoding RIPK4 was silenced in two melanoma cell lines A375 and WM266.4 cells using the CRISPR/Cas9 technique." (PMID 39766280, 2024). "In cutaneous SCC and melanoma several nonsense, frameshift and missense mutations occur mainly in the kinase and ankyrin domains of RIPK4." (PMID 37688617, 2023). "RIPK4 has been implicated in the progression of numerous tumors; however its role in melanoma remained unresolved." (PMID 34768934, 2021). "RIPK4 exerts its inducing effect on melanoma invasiveness via NF-κB signaling; however, high susceptibility of NF-κB pathway to other signaling pathways (incl." (PMID 34768934, 2021). "The question of whether RIPK4 levels affect cisplatin sensitivity more in melanoma cells with BRAF mutations than in those with NRAS or BRAF wild-type mutations warrants further investigation in future studies." (PMID 39766280, 2024). "This cell context-dependent involvement of RIPK4 in melanoma cell invasiveness, together with the suppressive function(s) of RIPK4 at the early stages of melanoma, apparently underlie the lack of straightforward correlation between RIPK4 levels and melanoma progression." (PMID 34768934, 2021). "Increased RIPK4 levels in metastatic melanoma biopsies prompted us to investigate the consequences of RIPK4 loss for the invasive and metastatic phenotype of melanoma cells." (PMID 41660747, 2026). "An hyperactive NF-κB pathway maintains the malignant behavior of melanoma, which can be influenced by both RIPK4 and activated VDR." (PMID 40490050, 2025). "Downregulation of Receptor-Interacting Protein Kinase 4 (RIPK4) inhibits NF-κB and Wnt/β-catenin signaling in melanoma and xenograft growth in mice." (PMID 40490050, 2025). "Our results have shown that both siRIPK4 and CRISPR/Cas9-mediated RIPK4 knockout increase VDR expression in melanoma cells." (PMID 40490050, 2025). "We showed that RIPK4 is involved in signal transduction through the NFκB and Wnt/β-catenin pathways, regulating the Wnt3A-induced invasive potential of melanoma cells and the growth of xenografts in mice." (PMID 39766280, 2024). "Our previous data indicate that various melanoma cell lines exhibit a wide range of RIPK4 expression levels, ranging from high (WM266.4, SKMEL-28), medium (A375) to low (BLM), as described." (PMID 39766280, 2024). "Global analysis of gene expression changes upon RIPK4 silencing reveals a complex role for this kinase in regulating adhesion, migration, proliferation, and inflammatory processes in melanoma cells." (PMID 39766280, 2024). "RNA sequencing technology (RNA-Seq) was used to characterize global transcriptome changes after silencing of RIPK4 in WM266.4 melanoma cells, in which the transfection efficiency was approximately 80%." (PMID 38656555, 2024). "Our previous studies have shown that downregulation of RIPK4 impairs signalling pathways important for the survival and progression of melanoma, such as NFκB and Wnt/β-catenin, which are also involved in the regulation of ABCG2 protein levels." (PMID 39766280, 2024).
melanoma (continued). "The positive correlation observed between RIPK4 expression levels and the number of p65-positive cells, as well as the intensity of p65 fluorescence in melanoma biopsies, further confirms the link between RIPK4 expression and NF-κB activation." (PMID 38656555, 2024). "To investigate the molecular function of the RIPK4 protein in melanoma cells, we performed a transcriptome analysis of WM266.4 cells with silencing of this kinase." (PMID 38656555, 2024). "In this study, we confirmed using RNA-seq analyses that RIPK4 is potentially involved in key biological processes such as cell adhesion, migration, proliferation, differentiation, and inflammatory processes in melanoma." (PMID 38656555, 2024). "Our previous studies confirmed that RIPK4 is heterogeneously expressed in melanoma specimens and cell lines." (PMID 39766280, 2024). "In our prior study, we demonstrated heterogeneous expression of RIPK4 in melanoma samples, where it acts as an oncogene, in contrast to cutaneous squamous cell carcinoma, where it functions as a tumor suppressor." (PMID 38656555, 2024). "Global transcriptome analysis of WM266.4 melanoma cells with silencing of RIPK4 confirmed the significant role of RIPK4 kinase in melanoma cell transformation and development." (PMID 38656555, 2024). "This suggests a relatively minor impact of IRF6 and ELOVL4 in melanoma, further emphasizing the context-dependent role of RIPK4 in both non-melanoma and melanoma skin cancers." (PMID 38656555, 2024). "The abnormal expression of Receptor-Interacting Protein Kinase 4 (RIPK4) in certain melanomas contributes to tumour growth through the NFκB and Wnt/β-catenin signalling pathways, which are known to regulate chemoresistance and recurrence." (PMID 39766280, 2024). "In conjunction with a previous study, our data unveil the complex role of RIPK4 in regulating immune signaling networks in melanoma cells." (PMID 38656555, 2024). "The transcriptome analysis revealed the regulatory role of RIPK4 in the invasive potential of melanoma cells by participating in the regulation of the expression of numerous genes crucial for metastasis." (PMID 38656555, 2024). "The receptor-interacting protein kinase (RIPK4) has an oncogenic function in melanoma, regulates NF-κB and Wnt/β-catenin pathways, and is sensitive to the BRAF inhibitors: vemurafenib and dabrafenib which lead to its decreased level." (PMID 38656555, 2024). "Global analysis of gene expression changes indicates a complex role for RIPK4 in regulating adhesion, migration, proliferation, and inflammatory processes in melanoma cells." (PMID 38656555, 2024). "Summarizing, our recent data confirm our previous findings, indicating a correlation between NF-κB activation and RIPK4 expression in melanoma patient specimens." (PMID 38656555, 2024). "Since PEBP1 acts as a tumor suppressor in melanoma, we investigated a correlation between the levels of RIPK4 and PEBP1 protein levels in melanoma." (PMID 36765875, 2023). "Second, we showed that vemurafenib and dabrafenib led to the downregulation of the RIPK4 protein in A375 and WM266.4 melanoma cells that carry BRAFV600E/D mutations." (PMID 36765875, 2023). "The role of RIPK4 in melanoma is limited to our recent studies indicating an oncogenic role for this kinase in melanoma." (PMID 36765875, 2023). "Since receptor-interacting protein kinase (RIPK4) probably functions as an oncogene in melanoma and its structure is similar to the BRAF protein, we analyzed the impact of vemurafenib and dabrafenib on RIPK4 in melanomas." (PMID 36765875, 2023). "The analyses performed in this study confirm previous reports on the involvement of RIPK4 in the regulation of the cell cycle of WM266.4 melanoma cells." (PMID 36765875, 2023). "Involvement of RIPK4 in the NFκappaB transduction pathway affects migration, invasive potential and proliferation of melanoma cells." (PMID 36765875, 2023).